FUS (FUS RNA binding protein)
Diseases named in the same sentence as FUS in open-access papers (continued):
Sharing a sentence is not in itself a finding about the gene and the disease.
frontotemporal dementia (continued). "FTD syndromes are characterized by lobar atrophy (frontotemporal lobar degeneration or FTLD) and the presence of either cellular TDP43 (FTLD-TDP), tau (FTLD-tau), or FUS aggregates, while extracellular β-amyloid plaques and hyperphosphorylated tau tangles develop in AD." (PMID 30467822, 2019). "FUS is a DNA/RNA-binding protein involved in both ALS and frontotemporal dementia (FTD)." (PMID 31515480, 2019). "Importantly, aggregation of misfolded FUS or TDP-43 is also characteristic of several neurodegenerative disorders in addition to ALS, including frontotemporal lobar degeneration." (PMID 25792726, 2015). "While FUS and TDP-43 are normally located in the nucleus, FUS-positive and TDP-43-positive cytoplasmic inclusions are pathological hallmarks of most non-SOD1 sALS cases and a related neurological disorder, frontotemporal lobar degeneration (FTLD)." (PMID 25792726, 2015). "Neuropathological classification of Frontotemporal Dementia (FTD) is based on the major constituents of the cellular inclusions present, such as tau, TAR-DNA-binding protein-43 (TDP-43) or fused-in-sarcoma (FUS) protein, designated FTLD-tau, FTLD-TDP or FTLD-FUS respectively." (PMID 25188321, 2014). "Furthermore, spatial dissociation of nuclear SFPQ and FUS, which normally form a high–molecular weight (HMW) complex, causes increased four-repeat tau isoform expression, which, in turn, leads to frontotemporal dementia (FTD)–like phenotypes in mice and neurodegeneration in human cortical neurons." (PMID 40845103, 2025). "Currently, four molecular subgroups of frontotemporal lobar degeneration (FTLD) have been established with FTLD-Tau being characterized by Tau depositions, FTLD-TDP by TDP-43 aggregates, and FTLD-FET by protein abnormalities of the FET (FUS, EWS, and TAF15) protein family." (PMID 34561610, 2021). "Considering its role in splicing regulation and in neurodegenerative disorders such as ALS and frontotemporal dementia, the study of FUS in circRNA biogenesis is important not only to elucidate its role in this process but also to link circRNA function to neurodegenerative processes." (PMID 28358055, 2017). "In addition to ALS, rare forms of frontotemporal lobar degeneration (FTLD) also exhibit tau-negative, TDP-43 negative, FUS-positive inclusions in the absence of FUS mutations." (PMID 24027631, 2013). "The recent discovery of mutations in TAR DNA-binding protein-43 (TDP-43) and Fused in sarcoma (FUS, also named TLS) in both familial ALS and frontotemporal dementia (FTD) has shifted research into disease mechanisms and potential therapeutics." (PMID 22363618, 2012). "4G8 staining to detect β-amyloid pathology and TDP-43 and FUS staining for frontotemporal dementia (FTD) pathology were all negative." (PMID 33579389, 2021). "Since then, non-mutant FUS has been identified in cytoplasmic inclusions in cortical neurons of a subset of patients with frontotemporal dementia (FTD; the neuropathological diagnosis is termed frontotemporal lobar degeneration (FTLD-FUS))." (PMID 29547565, 2018).
sarcoma (163 papers, 2008 to 2026). A usually aggressive malignant neoplasm of the soft tissue or bone. "Third, PAPPA2, encoding the IGFBP5-specific proteinase pappalysin 2, was among the recurrently mutated genes in FUS/EWSR1-TFCP2 sarcoma." (PMID 38168093, 2024). "Familial ALS is known to be caused by SOD1 (superoxide dismutase 1) and FUS (fused in sarcoma) mutations." (PMID 37545694, 2023). "The Nup98FG85 fibril structures are predicted to have higher stability than the amyloid fibrils formed by the low-complexity region of the stress granule-associated protein fused in sarcoma (FUS)." (PMID 36138110, 2022). "Most common are mutations in C9orf72 (chromosome 9 open reading frame 72), SOD1 (superoxide dismutase 1), FUS (fused in sarcoma), and TARDBP (encoding for TDP-43)." (PMID 35777956, 2022). "Recent evidence also indicates that the function of some cellular condensates such as P granules, stress granules, and puncta formed by FUS (fused in sarcoma) have underlying organisational principles." (PMID 35796545, 2022). "FUS (fused in sarcoma) is a representative ALS-linked RNA-binding protein (RBP) that specifically recognizes G-quadruplex (G4)-DNA/RNAs." (PMID 34624313, 2021). "For example, mutations in the gene encoding ATM (ataxia telangiectasia mutated) can lead to the development of AT or breast cancer, while mutations in the gene encoding FUS (fused in sarcoma) cause ALS and sarcomas." (PMID 33584810, 2020). "The FET protein family consists of fused in sarcoma (FUS), Ewing sarcoma (EWS) and TATA-binding protein associated factor 15 (TAF15) and was first discovered as components of fusion oncogenes causing specific malignancies." (PMID 31659510, 2019). "Fused in sarcoma aggregation is a hallmark of FUS-ALS pathology, and it is believed that the recruitment of FUS to cytoplasmic SGs seeds its aggregation." (PMID 31695598, 2019). "Of the ~ 5% of ALS cases that lack TDP-43 pathology (TDP-43-negative ALS), a subset is the result of a mutation in FUS (fused in sarcoma)." (PMID 30157956, 2018). "Two years later another RNA binding protein termed fused in sarcoma (FUS) (also known as translated in sarcoma or TLS) was seen to be associated with a small number of ALS and FTLD cases, often in the young." (PMID 26452761, 2015). "Although we did not test this variant, a parallel substitution in the RNA binding protein fused in sarcoma (FUS) (R522G) caused a five-fold decrease in TPNO-1 binding and cytoplasmic mis-localization of FUS27." (PMID 25254102, 2014). "In the study of sarcomas caused by fusion of FUS with various transcription factors, overexpression of the transcription factor component alone was unable to promote tumor growth, suggesting that FUS is essential for the oncogenic role of FUS-fusion proteins." (PMID 25501833, 2014). "One of the RRM-containing human gene product that encodes for FUS protein (fused in sarcoma, 546 amino acids long), is predicted to possess only 50 amino acids, which form a folded structure." (PMID 25534245, 2014). "Shortly after the identification of mutations in TDP-43 in ALS cases, mutations in another gene encoding an RNA-binding protein, FUS (fused in sarcoma; also known as TLS, translocated in liposarcoma), were identified in cases with familial ALS (ALS-FUS)." (PMID 22724023, 2012). "The use of iSNs from patient iPSCs has helped address some of these difficulties, showing that Wnt signaling is elevated in C9ALS iSNs and in iSNs containing ALS-associated mutations in FUS (fused in sarcoma), and contributes to decreased synaptic protein numbers and cell death respectively." (PMID 38918634, 2024).
sarcoma (continued). "In these neural disorders, two RNA-binding proteins (RBPs), TDP-43 (43 kDa TAR DNA-binding protein) and FUS (fused in sarcoma), have been reported as the common causative gene products, of which modulations lead to a gain of functional toxicity or a loss of normal protein function." (PMID 34624313, 2021). "Human regulatory proteins HNRNPA1 (heterogeneous nuclear ribonucleoprotein A1), HNRNPC, HNRNPL, HuR (human antigen R), and protein LIN28A (lin-28 homolog A) were predicted to bind ebv-sisRNA-1 and/or ebv-sisRNA-2; FUS (fused in sarcoma) was predicted to associate with ebv-sisRNA-2." (PMID 29458410, 2018). "The efficacy of PRMT5 inhibitors in the context of MTAP passenger deletions has been demonstrated in several cancers, suggesting that patients with FUS/EWSR1-TFCP2 sarcoma and CDKN2A/MTAP loss may also benefit from PRMT5 inhibitors, which are currently being tested in clinical trials." (PMID 38168093, 2024). "FTD-FUS (FTD fused in sarcoma) and therapeutic strategies: Studies have demonstrated that treating cell cultures with methylation inhibitors may help decrease cytoplasmic mislocalization and aggregates associated with FUS mutants in FTD cases." (PMID 37629187, 2023). "In addition, the FET protein family, which includes the EWS, TAF15 (TATA-box binding protein associated factor 15), and FUS/TLS (fused in sarcoma/translocated in liposarcoma, herein referred to as FUS) proteins, has been shown to be a part of the splicing machinery." (PMID 33652741, 2021). "Trabectedin has been shown to have particular effect in translocation-associated sarcomas such as myxoid LPS, where preclinical research has shown that trabectedin can reverse the transcriptional reprogramming orchestrated by the pathognomonic FUS-CHOP fusion gene." (PMID 28332083, 2017). "RNA pull-down, RNA immunoprecipitation (RIP), and actinomycin D mRNA decay assays were conducted to elucidate the molecular interactions between lncRNA-PRLB, the RNA-binding protein fused in sarcoma (FUS), and glutathione peroxidase 4 (GPX4) mRNA." (PMID 41783067, 2026). "FUS (“Fused in sarcoma”) was initially identified as part of a chromosomal translocation in human liposarcomas where the FUS gene is fused to the gene CHOP, whereby the RNA-binding domains of FUS are replaced by the basic leucine zipper domain of CHOP." (PMID 40468389, 2025). "Translocations of FUS or EWSR1 can generate a large number of fusion proteins that drive several sarcomas, with the most notable being Ewing sarcoma." (PMID 40285687, 2025). "In the public HITS-CLIP dataset (GSE43308), fused in sarcoma (FUS) was identified as an RBP that binds to both MIR205HG and IL33 mRNA." (PMID 40059822, 2025). "Patient-derived iPSC neurons with mutant transactive response DNA binding protein 43 kDa (TDP-43) or fused in sarcoma (FUS) show disease-relevant phenotypes." (PMID 41311672, 2025). "Among the networks with mostly downregulated proteins, one cluster involved RNA-binding proteins surrounding FUS (fused in sarcoma) protein." (PMID 41210309, 2025). "For example, FUS (fused in sarcoma), a key regulator of RNA processing, is involved in RNA metabolism and stress response." (PMID 41285791, 2025). "Fused in sarcoma (FUS) forms phase-separated droplets that mediate its interaction with the Pol II CTD, and PRMT5-catalyzed symmetric dimethylation of FUS is required for its stable association with Pol II." (PMID 41204384, 2025). "The FET (FUS, EWSR1, and TAF15) fusion oncogenes are characteristic for around 20 different sarcomas and leukemia, including FUS::DDIT3 in myxoid liposarcoma (MLS) and EWSR1::FLI1 in Ewing sarcoma (EWS), the two most common FET sarcoma entities." (PMID 40988026, 2025). "Genes encoding the RNA-binding proteins FUS, EWSR1, and TAF15 (FET proteins) are involved in chromosomal translocations in rare sarcomas." (PMID 40852926, 2025).
sarcoma (continued). "Genes encoding the RNA-binding proteins FUS, EWSR1, and TAF15 (FET family proteins) are frequently involved in chromosomal translocations in sarcomas." (PMID 40852926, 2025). "The latest research findings and novel treatment approaches for EWSR1/FUS::NFATC2 sarcoma involve molecular pathology research, immunotherapy, targeted therapy, and gene-editing techniques." (PMID 38254207, 2024). "The second most common alteration in FUS/EWSR1-TFCP2 sarcomas, with an incidence of 75%, were deletions or indels of the CDKN2A tumor suppressor, which have been noted previously." (PMID 38168093, 2024). "Despite the limited number of cases, the observations in patients and ex vivo and in vitro drug response data support that ALK inhibitors should be further explored in FUS/EWSR1-TFCP2 sarcoma." (PMID 38168093, 2024). "Genetically, MLS belongs to a group of more than ten different sarcoma entities all defined by FET (FUS, EWSR1 and TAF15) fusion oncogenes, which are formed by the N-terminal part of FET genes fused to one of various transcription factor partners." (PMID 38671504, 2024). "Fused in sarcoma (FUS) is involved in the formation of nuclear biomolecular condensates associated with poly(ADP-ribose) [PAR] synthesis catalyzed by a DNA damage sensor such as PARP1." (PMID 39596510, 2024). "Due to the focal expression of epithelial markers such as CK and EMA in some cases of EWSR1/FUS::NFATC2 sarcoma, combined with morphological features, it can be easily misdiagnosed as an myoepithelioma." (PMID 38254207, 2024). "In contrast to other fusion-driven sarcomas, FUS/EWSR1-TFCP2-positive tumors exhibited substantially rearranged genomes, suggesting a defect in DNA repair." (PMID 38168093, 2024). "In terms of clinical characteristics, EWSR1/FUS::NFATC2 sarcoma mainly occurs in young males, with a male-to-female ratio of approximately 3:1." (PMID 38254207, 2024). "For example, EWSR1/FUS::NFATC2 sarcomas feature a marked male predilection, and EWSR1::PATZ1 sarcomas can arise in a broad age range, in contrast to Ewing sarcoma." (PMID 38339014, 2024). "In terms of prognosis, EWSR1/FUS::NFATC2 sarcoma typically requires treatment such as surgical resection, radiation therapy, and chemotherapy." (PMID 38254207, 2024). "Immunohistochemical staining shows that EWSR1/FUS::NFATC2 sarcoma often expresses markers such as CD99, NKX3.1." (PMID 38254207, 2024). "The most important differential diagnosis for EWSR1/FUS::NFATC2 sarcoma is classical Ewing's sarcoma." (PMID 38254207, 2024). "PTH1R encodes the parathyroid 1 receptor and, like IGFBP5, was also among the DEG upregulated in FUS/EWSR1-TFCP2 sarcoma compared with other RMS types." (PMID 38168093, 2024). "In terms of histology, EWSR1/FUS::NFATC2 sarcoma typically presents as an undifferentiated small round cell sarcoma." (PMID 38254207, 2024). "Although EWSR1/FUS::NFATC2 sarcoma has its unique FISH presentation, due to its rarity and non-exclusive molecular genetic features, the diagnosis of this tumor must be combined with histology and immunohistochemistry." (PMID 38254207, 2024). "FUS and EWSR1, participants in other sarcoma fusion oncogenes, are both implicated in familial ALS27–29." (PMID 38326311, 2024). "NKX2.2, which is a relatively specific marker for diagnosing Ewing sarcoma, can also be expressed in EWSR1/FUS::NFATC2 sarcoma." (PMID 38254207, 2024). "These research results and novel treatment approaches provide new insights and directions for the treatment and management of EWSR1/FUS::NFATC2 sarcoma." (PMID 38254207, 2024). "In recent years, with the development of next-generation sequencing technology, some tumors associated with EWSR1 gene rearrangements have shown unique histological and molecular genetic characteristics, such as EWSR1/FUS::NFATC2 sarcoma." (PMID 38254207, 2024).
sarcoma (continued). "In leukemic cells, the USP15 gene interacts with and stabilizes FUS (fused in sarcoma), a DNA repair factor, directly linking USP15 to the DNA damage response, demonstrating the importance of DUBs in preserving normal hematopoiesis." (PMID 37373211, 2023). "Among these five candidates, FUS (fused in sarcoma) was the most essential gene (βWT = 0.17; βRBKO = −0.61) in the initial CRISPR screen of ER+/RBKO cells." (PMID 37502925, 2023). "Our analysis also revealed two previously identified ALS-associated genes TBK1 (TANK binding kinase) (FDR = 0.063) and FUS (fused in sarcoma; FDR = 0.155) with a marginal statistical significance." (PMID 36835433, 2023). "The FUS gene, located on chromosome 16p11, consists of 15 exons and encodes the DNA/RNA-binding protein FUS/TLS (fused in sarcoma/translocated in sarcoma)." (PMID 36111771, 2023). "The protein FUS (FUSed in sarcoma) is a metazoan RNA-binding protein that influences RNA production by all three nuclear polymerases." (PMID 37690693, 2023). "Many studies have revealed that ALS-related RNA binding proteins (RBPs), such as TAR DNA-binding protein 43 (TDP-43) and fused in sarcoma/translocated in liposarcoma (FUS), regulate miRNAs processing in both the nucleus and cytoplasm." (PMID 36895420, 2023). "A fusion protein involving the DNA-binding domain of a transcription factor, such as DDIT3 or ERG, and the LC domain of FUS can redirect RNA Pol II activity sufficient to drive Ewing and other sarcomas." (PMID 37690693, 2023). "A study has shown that circFndc3b interacted with RNA-binding protein FUS in sarcomas to decrease FUS level, thereby upregulating vascular endothelial growth factor (VEGFA) expression and activating VEGFA signaling." (PMID 36991356, 2023). "To demonstrate condensate detection by DigitISA, we set out to probe the phase behavior of the protein fused in sarcoma (FUS) (see Methods: Protein preparation)." (PMID 36746944, 2023). "SFPQ, a specific DNA and RNA binding protein, is strictly related to neurodegenerative diseases because of its relationship with FUS protein (the neural homeostasis-binding fused in sarcoma)." (PMID 37446229, 2023). "The analysis also revealed two previously identified ALS-associated genes TBK1 (TANK binding kinase) (FDR = 0.063) and FUS (fused in sarcoma; FDR = 0.155), with marginal statistical significance." (PMID 36835433, 2023). "These interactions are perhaps reminiscent of a property shown by the RBPs fused in sarcoma (FUS) and TDP43 in promoting DNA repair by concentrating DSB signaling and repair factors." (PMID 35205152, 2022). "Several G4BPs, such as hnRNPs, nucleolin, CIRBP, TLS/FUS (translocated in liposarcoma, also known as fused in sarcoma), and EWS (Ewing’s sarcoma), have shared structural features, such as RNA recognition motifs (RRM) and RGG domains." (PMID 35625576, 2022). "For example, in paraspeckles, a nuclear phase condensate, NEAT1 (nuclear-enriched autosomal transcript 1) lncRNA acts as a scaffold, while the RNA binding protein, FUS (fused in sarcoma), is a client protein." (PMID 36035193, 2022). "For instance, inclusions containing the ubiquitinated RNA-binding proteins TDP-43 (TAR DNA-binding protein 43) or FUS (Fused in Sarcoma) can be found in patients of both diseases." (PMID 35777956, 2022). "With this tool, we confirmed that some known proteins containing LCRs such as ⍺-syn, tau and FUS (fused in sarcoma) had LCRs in their sequences." (PMID 35289333, 2022). "On the other hand, FUS::NFATC2-translocated sarcomas exhibited very complex genomic profiles, while in those cases harboring ESWR1::NFATC2 fusion, fewer genomic alterations were found." (PMID 36555836, 2022). "The fusion gene of ATF1 with EWSR1 or FUS is frequently reported in sarcomas including angiomatoid fibrous histiocytoma and clear cell sarcoma, which are relatively chemoresistant." (PMID 36860287, 2021).